RNF123 (ring finger protein 123)
Description:
Catalytic subunit of the KPC complex that acts as E3 ubiquitin-protein ligase. Promotes the ubiquitination and proteasome-mediated degradation of CDKN1B which is the cyclin-dependent kinase inhibitor at the G0-G1 transition of the cell cycle. Also acts as a key regulator of the NF-kappa-B signaling by promoting maturation of the NFKB1 component of NF-kappa-B: acts by catalyzing ubiquitination of the NFKB1 p105 precursor, leading to limited proteasomal degradation of NFKB1 p105 and generation of the active NFKB1 p50 subunit. Also functions as an inhibitor of innate antiviral signaling mediated by RIGI and IFIH1 independently of its E3 ligase activity. Interacts with the N-terminal CARD domains of RIGI and IFIH1 and competes with the downstream adapter MAVS.
Synonyms: KPC1; FP1477; FLJ12565
Tractability: PROTAC: UniProt records ubiquitination sites on it; ubiquitination databases record sites on it; its protein half-life has been measured.
Gene: Protein-coding gene on chromosome 3 (49,688,740 to 49,721,532, forward strand). Ensembl gene ENSG00000164068.
Subcellular location: Cytoplasm
Subcellular location (Human Protein Atlas): Cytosol
Pathways (Reactome):
Immune System: Antigen processing: Ubiquitination & Proteasome degradation
Metabolism of proteins: Ub-specific processing proteases
Gene Ontology:
Molecular function: protein binding; ubiquitin protein ligase activity; ubiquitin-protein transferase activity
Biological process: protein maturation; protein polyubiquitination; ubiquitin-dependent protein catabolic process; modification-dependent protein catabolic process; regulation of cell cycle; protein catabolic process; protein ubiquitination
Cellular component: cytoplasm; ubiquitin ligase complex; cytosol
Genetic constraint (gnomAD): Loss-of-function variants: 88 observed, 174.05 expected, observed/expected ratio (o/e) 0.51, 90% interval 0.43 to 0.6. The upper end of that interval is the gene's LOEUF score, 0.6, which puts it in group 2 of 6, group 1 being the genes least tolerant of losing a copy. Missense variants: 1,419 observed, 1,773.7 expected, observed/expected ratio (o/e) 0.8, 90% interval 0.76 to 0.84. Synonymous variants: 666 observed, 707.65 expected, observed/expected ratio (o/e) 0.94, 90% interval 0.88 to 1.
Homologues: Orthologues: chimpanzee RNF123 (99% identical), macaque RNF123 (99% identical), dog RNF123 (94% identical), pig RNF123 (94% identical), mouse Rnf123 (94% identical), guinea pig RNF123 (93% identical), rat Rnf123 (91% identical), tropical clawed frog rnf123 (78% identical), zebrafish rnf123 (75% identical), Drosophila melanogaster Kpc1 (31% identical). Paralogues in human: RSPRY1 (8% identical).
Diseases named in the same sentence as RNF123 in open-access papers:
RNF123 is named in the same sentence as 32 diseases in open-access papers, as found by Europe PMC text mining. Sharing a sentence is not in itself a finding about the gene and the disease. The quoted sentences say what the papers report.
melanoma (8 papers, 2018 to 2025). A malignant, usually aggressive tumor composed of atypical, neoplastic melanocytes. "In a previous report from our group, we found that miR-155-5p specifically targets RNF123 and reduces its expression in melanoma." (PMID 32349217, 2020). "Besides, several studies also showed that RNF123 may have a role in cancer, including aggressive glioblastoma and melanoma." (PMID 34650599, 2021).
glioblastoma (6 papers, 2018 to 2023). The most malignant astrocytic tumor (WHO grade IV). "This study examined the role of the ubiquitin E3-ligase RNF123 in modulating downstream NF-κB1 targets in glioblastoma (GB) tumor progression." (PMID 32349217, 2020). "RNF123 acts as a major tumor suppressor factor except in metastatic melanoma and glioblastoma." (PMID 33966052, 2021). "Consistent with a decrease in RNF123 expression in metastatic tumor cell lines and tissues previously reported, we observed a significant reduction in H3K27Ac in metastatic melanoma and glioblastoma cell lines compared to primary melanocytes." (PMID 33966052, 2021). "Previous study showed that PAI-1 is a downstream target that is negatively regulated by Ubiquitin-E3 Ligase RNF123, and PAI-1 knockdown reduced the proliferation and invasion of glioblastoma cell lines." (PMID 37726265, 2023).
breast carcinoma (3 papers, 2018 to 2022). "In reviewing the literature, no data were found on the association of breast cancer with PCGF1, RNF123, GRWD1, USP30, ATXN3L, and PARP11." (PMID 36685836, 2022).
depression (3 papers, 2015 to 2021). "In addition, RNF123 was also reported to be dysregulated in depression and may serve as a clinical biomarker for depression." (PMID 34650599, 2021).
metastatic melanoma (3 papers, 2020 to 2025). A melanoma that has spread from its primary site to another anatomic site. "Recently, we demonstrated that RNF123 in the context of tumor progression was downregulated in metastatic melanoma functioning as a tumor suppressor gene." (PMID 32349217, 2020).
brain tumors (1 paper, 2020). "By using the RNA-sequencing data from the TCGA dataset for GB, brain tumors with IDH WT status showed a significant reduction in RNF123 expression compared to normal brain tissue, but not in IDH mutated GB compared to normal brain tissue." (PMID 32349217, 2020).
cutaneous melanoma (1 paper, 2020). A primary melanoma arising from atypical melanocytes in the skin. "Our studies demonstrated the role of miR-155-5p in blocking RNF123 expression in GB cells, an observation that we also described in cutaneous melanoma cells." (PMID 32349217, 2020).
Emery-Dreifuss muscular dystrophy (1 paper, 2020). Emery-Dreifuss muscular dystrophy (EDMD) is characterized by muscular weakness and atrophy, with early joint contractures and cardiomyopathy. "Interestingly, the authors found that expression of lamin A rod-domain mutants associated with the Emery-Dreifuss muscular dystrophy (EDMD), G232E, Q294P and R386K, considerably increased the expression of RNF123, which was associated with decreased protein levels of lamin B1, LAP2α and pRb." (PMID 32471220, 2020).
fibromyalgia (1 paper, 2023). A chronic disorder of unknown etiology characterized by pain, stiffness, and tenderness in the muscles of neck, shoulders, back, hips, arms, and legs. "Several genes/loci have been reported more than once in CWP, fibromyalgia, and MCP, including EXD3, SLC39A8, AMIGO3/GMPPB/RNF123, C6orf106, FAF1, SLC24A3, and LINC01065/LINC00558." (PMID 37144689, 2023).
mental disorder (1 paper, 2021). A disease that has its basis in the disruption of mental process. "However, the function of RNF123 in the human central nervous system and the corresponding mechanisms about how it confers the risk of mental disorders remain to be investigated." (PMID 34650599, 2021).
tumor (15 papers, 2016 to 2025). "Our study demonstrated the importance of RNF123 in modulating the activation of the SerpinE1 and relation to GB tumor progression." (PMID 32349217, 2020). "In the present study, we hypothesized that RNF123 aberrant expression in IDH WT GB affects NF-κB1 processing and downstream targets, promoting GB tumor progression." (PMID 32349217, 2020).
cancer (9 papers, 2019 to 2025). A tumor composed of atypical neoplastic, often pleomorphic cells that invade other tissues. "The authors focused on a specific editing event, namely, A22G in KPC1 (RNF123, ring finger protein 123), showing that this may be regulated by ADAR1 and was involved in cancer-related processes, both in vitro and in vivo." (PMID 39199659, 2024).
RNF123 also shares sentences with these, for which no sentence is quoted: Pancreatic Tumor (3 papers); prostate carcinoma (2); Anxiety (1); bone osteosarcoma (1); brain disorder (1); cardiovascular diseases (1); cholangiocarcinoma (1); dementia (1); glioma (1); infection (1); intrahepatic cholangiocarcinoma (1); ischemia (1); lung carcinoma (1); musculoskeletal system diseases (1); neurological disorders (1); pancreatic cancer (1); Rett syndrome (1); schizophrenia (1); Sézary syndrome (1); squamous cell cancers of (1).